SSTR2 (somatostatin receptor 2)
Diseases named in the same sentence as SSTR2 in open-access papers (continued):
Sharing a sentence is not in itself a finding about the gene and the disease.
tumor (continued). "Although the radiotracer tumor uptake is increased in mice injected with VPA eight hours prior to [177Lu]Lu-DOTATATE administration, this is not the result of SSTR2 upregulation, but most likely caused by other mechanisms, such as an increased [177Lu]Lu-DOTATATE circulation time and renal toxicity." (PMID 35057069, 2022). "If this is proven to be effective for SSTR2 upregulation, effort could be made to increase the low tumoral VPA dose, e.g., by the use of a constant-rate infusion system, allowing for stable blood concentrations or by applying a tumor-targeting approach." (PMID 35057069, 2022). "Hence, the tumor-to-organ ratio will increase as normally the expression of SSTR2 in non-tumor organs remains unchanged." (PMID 36559060, 2022). "However, this is limited in tumours without SSTR2 expression and by lack of widespread availability of 68Ga PET-CT." (PMID 33494364, 2021). "Additionally, immunohistochemical analysis indicated that SSTR2 was expressed in the tumor, but Bcl2 was not (p-Group H)." (PMID 33962620, 2021). "SSTR2 expression did not vary between tumor sites but correlated within patients." (PMID 33922482, 2021). "The overexpression of the tumor targets SSTR2 in NETs could increase the effectiveness of PRRT without increasing the toxicity profile." (PMID 34681229, 2021). "Furthermore, compared with 800CW-TATE-injected H69 xenograft bearing mice, IRDye800CW carboxylate-injected H69 xenografted mice had 83.4 ± 4.8% reduction, and SSTR2 negative CH-157MN xenograft bearing mice showed a reduction of 78.4 ± 4.8% tumor uptake." (PMID 33768405, 2021). "To best of our knowledge, there is no report suggesting that the expression of SSTR2 or Bcl2 relates to tumor malignancy, and we believe that this new method may be useful for IHCC classification." (PMID 33962620, 2021). "When SSTR2 immunohistochemical expression was scored either positive or negative, all [68Ga]Ga-DOTANOC-avid tumors (n = 22/23) expressed membranous SSTR2 and the only [68Ga]Ga-DOTANOC-negative tumor did not express membranous SSTR2 (Spearman’s rho −1.000, p = 0.043)." (PMID 35008325, 2021). "Notably, SSTR2 expression was also found to be low or absent in an additional 46 tumour samples, including 23 TK-mutant GIST and an additional 23 wtGIST samples." (PMID 33443647, 2021). "However, a subset of patients with low SSTR2 and high AGTR1 expression could benefit from tumor targeting approaches based on AGTR1 ligands." (PMID 33120925, 2020). "The tumor cells were absent of immunoreactivity of SSTR-2 (score 0)." (PMID 31511024, 2019). "In contrast, specific tracer uptake was observed in mice treated with SSTR2-F292A CAR T cells, demonstrating the expansion and contraction phases in the lungs, with peak CAR T cell signal occurring approximately 4 days following peak tumor burden and gradually decreasing to background levels." (PMID 29085043, 2017). "Since SSTR2 has been known to be most commonly expressed in various NETs and possesses the highest affinity for natural SST and synthetic SST analogs, most experiments utilize hSSTr2 reporter gene to transfect targeted tumor cells alone or together with other therapeutic genes." (PMID 25879040, 2015). "Significantly higher blood and kidney activity in the blockade group was also observed, contrasting most but not all previous reports that compare preclinical biodistribution of SSTR2 radiotracers in blockade and non-blockade groups of SSTR2-positive tumour-bearing mice." (PMID 26452495, 2015). "No increase in SSTR2 positivity could be observed in tumour xenograft sections at any time after treatment with177Lu-DOTA-Tyr3-octreotate." (PMID 22214480, 2011). "We observed no increase in SSTR2 staining in the tumour xenograft after treatment." (PMID 22214480, 2011). "However, other somatostatin analogues such as Lanreotide, which have good affinity for SSTR5 in addition to that for SSTR2, may advantageously recognize SSTR5 expressing tumours." (PMID 21143993, 2010).
tumor (continued). "Previous studies had shown stronger distributions of transcripts for SSTR2 in cancer prostate without correlation between mRNA of SSTR2 and Gleason grade in appearance contradiction with our results, which shows a diminished protein expression with an increase in tumor Gleason grade." (PMID 19365586, 2009). "In this context, new grading systems for EOR incorporating postoperative PET/CT or PET/MRI findings have already been proposed, but prospective validation is still lacking, and prognostic relevance of postoperative SSTR2 PET/CT for tumor recurrence ultimately remains unclear." (PMID 37642702, 2023). "Due to some heterogeneity in GOT1 tumors, there is a risk that a mouse may be transplanted with a tumor piece having cells with altered SSTR expression, which was most probably the case in the present study, and explains the lower SSTR2 expression in this non-responding mouse." (PMID 35008397, 2022). "Thus, the SSTR2 expression in tumor samples did not significantly change in metastases." (PMID 33922482, 2021). "Immunohistochemical results showed that the tumor cells expressed Vimentin, SMA, Bcl-2, CD56, CD34, CD31, Ki-67, ERG, RB, INI-1, and SATB2, but were negative for SSTR2 and CK." (PMID 40406261, 2025). "Despite a similar tumor uptake of [[64Cu]Cu-DOTA-TATE], slower blood and heart clearance, along with significantly higher uptake in SSTR2-negative organs, was observed." (PMID 40430268, 2025). "The important point, however, is that although patients are selected based on SSTR2 positivity by [68Ga]Ga-DOTA-TATE PET/CT, they are not specifically chosen to receive inhibitors based on their tumor profile." (PMID 38164150, 2024). "The receptor binding properties and tumor targeting were examined both in vitro and in vivo by using NCI-H727 (SSTR2/FAP, positive) and Mc38 (SSTR2/FAP, negative) cell lines and tumor-bearing mouse models." (PMID 39770488, 2024). "In this case, SSTR2 was expressed in both immunohistochemically positive and negative LMP-1 tumor regions." (PMID 37847488, 2023). "Ex vivo imaging showedcomparable fluorescence in SSTR2+ tumors with both conjugates, butin the absence of SSTR2, only the FNIR-Tag conjugate produced theexpected decrease in tumor signal, an observation that extended toall normal tissues except the kidney." (PMID 36174110, 2022). "We measured, on average, a slight increasein tumor uptake with MMC(FNIR-Tag)-TOC and a >60% signal reductionin tumors lacking SSTR2 and in most nontarget tissues, including thoseassociated with NET surgery (e.g., pancreas, small intestine)." (PMID 36174110, 2022). "Immunohistochemical staining of the tumour was positive for Renin, CD34, Vimentin, and synaptophysin (Syn) and negative for somatostatin receptor 2 (SSTR2) and chromogranin A (CgA)." (PMID 35303838, 2022). "In summary, SSTR2, as well as PSMA are nonspecific markers found in many tumor entities with variable expression patterns." (PMID 35546652, 2022). "In this study, SSTR2 expression was demonstrated to be low or absent for each of the 11 cases of metastatic wtGIST analysed using [68 Ga]Ga-DOTATATE PET/CT and in tumour samples from 8/12 patients using SSTR2 IHC." (PMID 33443647, 2021). "In our cellular studies in vitro with high SSTR2-expressing NCI-H727 cells, tumor perfusion is not a confounding factor, but we nonetheless observed a modest but significant increase in the receptor-mediated uptake of LuTate after chemotherapy." (PMID 33435224, 2021). "Radiolabeled SSTR2 antagonists, such as 177Lu-satoreotide tetraxetan, have shown higher tumor uptake, independent of SSTR activation, and greater tumor-to-organ ratios than agonists in preclinical models." (PMID 33916707, 2021). "Of the 14 tumors that expressed SSTR2, 1 had a NETPET score of 1, 6 had a NETPET score of 2, 1 had a NETPET score of 3, 1 had a NETPET score of 4, and the only tumor classified NETPET score of 5 did not express SSTR2 (Spearman’s rho −0.406, p = 0.043)." (PMID 35008325, 2021).
tumor (continued). "Tumour tissue for SSTR2 IHC was performed on 54 tumour samples and this included tumour samples from 8/12 (66.6%) patients who had [68 Ga]Ga-DOTATATE PET/CT imaging and 47 tumour samples from individuals who did not have [68 Ga]Ga-DOTATATE PET/CT imaging." (PMID 33443647, 2021). "In conclusion, the protein expression of SSTR2, but not of SSTR5, is a valuable indicator in predicting biochemical and tumor size response to short-term SSA treatment in acromegalic patients." (PMID 28396686, 2017). "It binds to a wide range of SSTR subtypes (SSTR2, SSTR3, and SSTR5) and has shown promise in diagnosing a variety of tumor types, including some OctreoScan negative NETs." (PMID 25879040, 2015). "The results of RT-PCR demonstrated that SSTR2 and SSTR5 mRNAs existed abundantly in all 5 tumor cell lines, except for a lack of SSTR5 in MOLT-4 cells." (PMID 21892324, 2008). "Moreover, we observed that lower SSTR1 and SSTR2, but not CORT, expression levels were also displayed in tumours harbouring EGFR amplification, another aggressive sign in GBM, in the Gravendeel-cohort." (PMID 40268793, 2025). "Additionally, G-CIMP negative tumours (representing a more aggressive GBM phenotype) have significantly lower expression levels of SSTR1 and/or SSTR2, but not CORT (data not shown), in the TCGA/Gravendeel/Murat-cohorts." (PMID 40268793, 2025). "Nevertheless it may be worth assessing expression of both SSTR2 and SSTR5, especially in the metastatic setting, regardless of the primary tumour status to evaluate response to SSAs and to better select patients for treatment." (PMID 36980746, 2023). "Consistent with the SSTR2 mRNA findings, the D341 and BON models demonstrated markedly higher receptor staining when grown in vivo than in vitro but no SSTR2 staining was detected in the U87MG or SK-N-MC tumours." (PMID 32576907, 2020). "The absent SSTR avidity despite positive SSTR2 immunohistochemistry in the appendiceal lesion may arise from spatial resolution limitations of 68Ga-PET/CT, detection of sub-threshold receptor expression by IHC, or sampling bias from tumor heterogeneity." (PMID 41333794, 2025). "The enrichment of deletions in tumor suppressor loci involved in cell adhesion and EMT regulation further supports the hypothesis that SSTR2 expression is not merely a biomarker but may reflect or contribute to a genetically and phenotypically aggressive subtype of HCC." (PMID 41002582, 2025). "Furthermore, in human reporter gene systems, such as SSTR2 or PSMA, target expression is not restricted to the engineered T cells, and tracer uptake in normal tissues, tumor tissues or tumor microenvironment expressing the target is seen, thus limiting specificity of uptake." (PMID 37908719, 2023).
cancer (84 papers, 2008 to 2026). A tumor composed of atypical neoplastic, often pleomorphic cells that invade other tissues. "Elevated expression of SSTR2 has been associated with favorable clinical outcomes in various human cancers." (PMID 41002582, 2025). "In this study, we found that high expression of SSTR2 is associated with an activated immune microenvironment across multiple cancers." (PMID 35264912, 2022). "Our study explored the association between SSTR2 expression and immune signatures with ICIs treatment efficacy across multiple cancers." (PMID 35264912, 2022). "Somatostatin receptor 2 (SSTR2) is a human somatostatin receptor and is highly implicated in hormone disorders, cancers, and neurological diseases." (PMID 35446253, 2022). "We then analyzed whether SSTR2 expression was associated with the efficacy of ICIs across multiple types of cancer." (PMID 35264912, 2022). "Further in vivo investigations are needed to elucidate whether the loss-of-function of SSTR2 recruits inflammatory cells via pathways that connect inflammation and cancer." (PMID 36551669, 2022). "Moreover, SSTR2 mRNA has also been associated with cancer related death." (PMID 38203605, 2023). "The NETest is a liquid biopsy test for NENs that improves the accuracy of cancer molecular diagnosis by detecting NET-associated genes, such as Ki-67, SSTR1, and SSTR2 expression levels through reverse transcription polymerase chain reaction." (PMID 38835066, 2024). "SSTR2-SST is also one of the axes with the strongest literature support for a role in cancer, along with several others, including MC1R-POMC and GHRHR-GHRH." (PMID 38723607, 2024). "In the following section, all experience, preclinical and clinical, with TAT of SSTR2-overexpressing cancers is critically reviewed." (PMID 38543120, 2024). "The published literature relating to TAT of SSTR2-overexpressing cancers was reviewed via keyword database search (Pubmed, Web of Science, Ovid)." (PMID 38543120, 2024). "177Lu-DOTATOC is a patent-free radioligand, molecularly recognized by somatostatin receptors (SSTR-2) overexpressed in cancer cells of about 80% of patients with metastatic gastroenteropancreatic neuroendocrine tumors (GEP-NET)." (PMID 37514174, 2023). "The first clinical application of 177Lu based PRRT was designed to target cancers that overexpressed somatostatin receptors type 2 (SSTR2)." (PMID 37111725, 2023). "OCT blocks cell proliferation in human hepatocyte-derived cancer cell line HepG2 via SSTR2, -3 and -5 and in a PTP-dependent pathway." (PMID 38203605, 2023). "Our findings suggest that high SSTR2 expression is accompanied by an actived immune microenvironment in various cancers." (PMID 35264912, 2022). "Median type 1 helper cell scores in SSTR2-high groups were higher than those of SSTR2-low groups in all 26 cancers." (PMID 35264912, 2022). "Five types of cancer express SSTR2 mildly (positive rate: 25%–50%), while the remaining two types of cancer barely stained SSTR2-positive (positive rate: 0%–24%)." (PMID 35264912, 2022). "BON1 and QGP1 cell lines both express SSTR2 at a relatively low level, despite mRNA levels greater than that seen in other cancer types and expression of SSTR2 is inversely related to the level of CpG island methylation." (PMID 35747820, 2022). "Our results show that the interleukin 15 pathway appeared to increase in activity in SSTR2-high groups in 92.31% of cancers, and the interleukin 2 pathway appeared to increase in activity in SSTR2-high groups in 96.15% of cancers." (PMID 35264912, 2022). "Our findings suggested that SSTR2 expression varies and is widely distributed across multiple cancer types." (PMID 35264912, 2022). "To investigate the expression of SSTR2 in different cancers, we consolidated the IHC data from the HPA." (PMID 35264912, 2022). "Among the five SSTRs, SSTR2 is aberrantly expressed in many cancer cells and tumor blood vessels, and it suppresses cancer growth and promoted cell apoptosis." (PMID 35595746, 2022).
cancer (continued). "In this study, we investigate the expression of SSTR2 across multiple types of cancer by collecting SSTR2 IHC data from the Human Protein Atlas (HPA)." (PMID 35264912, 2022). "In TCGA analysis, immune cell signatures and immune function pathways were enriched in high SSTR2 expression groups in most cancers." (PMID 35264912, 2022). "Five cancers express SSTR2 mildly (positive rate: 25%–50%) and two cancers barely expressed SSTR2 (positive rate: 0%–24%)." (PMID 35264912, 2022). "Both CA20948 and SSTR2-transfected U2OS cells are routinely used in preclinical studies concerning cancers overexpressing SSTR2." (PMID 36559060, 2022). "For instance, our group previously has shown that cancer cells overexpressing somatostatin receptor 2 (a commonly overexpressed receptor in NETs), synergistically sensitized to TRT when also treated with olaparib in vitro." (PMID 35887398, 2022). "Both lanreotide and octreotide showed specific binding to SSTR2 and played pharmacological roles in suppressing cell proliferation, cancer growth, and angiogenesis." (PMID 35595746, 2022). "HIVEP2 is a transcription factor whose downstream target, SSTR2, inhibits cancer cell proliferation." (PMID 34246306, 2021). "Summarizing, these data demonstrated that, in line with the epigenetic regulation involved in SSTR2 expression in NETs, the epigenetic machinery plays an important role in the regulation of multiple SSTRs in other cancer types as well." (PMID 33085037, 2021). "With this rationale, a phase I/II study (NCT02936323) is currently exploring the activity of PEN-221 in SSTR2-expressing advanced cancers including NETs, pheochromocytomas and SCLC." (PMID 33916707, 2021). "Several high affinity analogues of somatostatin have been developed as tracers and are routinely used for imaging SSTR2 overexpressing cancers in the clinical setting." (PMID 34439195, 2021). "PEN-221 is a peptide–drug conjugate designed to target cancer cells via an SSTR2-targeting ligand conjugated to the antimicrotubular cytotoxic agent, DM1." (PMID 33916707, 2021). "Positive SSTR2 expression in cancer cells was present in 26 out of 52 IHCC cases (50.0%) and positive Bcl2 expression in cancer cells was present in 19 (36.5%)." (PMID 33962620, 2021). "This is in contrast to SSTR2, which was more selectively overexpressed by cancer cells, but SSTR2-targeting DOTATATE was inferior for delivery purposes, as can be explained by low expression of the receptor." (PMID 28542563, 2017). "Our present data confirms that SSTR2 is upregulated in cancer versus normal cell lines by a factor of 10- to 10,000-fold, however the SSTR2 expression levels in cancer cells were very low compared to the reference, also in the two NSCLC cell lines." (PMID 28542563, 2017). "Somatostatin receptor 2 and nucleolin are known to be overexpressed by various cancer types, which have elicited comprehensive efforts to explore their therapeutic utilization." (PMID 28542563, 2017). "In C6 glioma, activation of SSTR2 by various somatostatin analogs led to a strong inhibition of in vivo cancer cell proliferation, intratumoral neoangiogenesis and Ki-67 expression." (PMID 25010045, 2014). "Our data suggest that mechanistically these effects are mediated by increased cancer cell proliferation in cells with down-regulated SSTR2." (PMID 25010045, 2014). "In this regard, an array of additional investigations of the use of peptide 5 (10 times more stable in serum than SRIF and 10-fold more active against SSTR2 than octreotide) in receptor-targeted anti-cancer therapy is currently underway in our laboratory." (PMID 24287991, 2013). "Importantly, they also retained the patient's somatostatin receptor 2 (SSTR2) expression pattern in cancer cells, which is the target of radioligand therapy." (PMID 41744372, 2026).